PLCG2 (phospholipase C gamma 2)
Diseases named in the same sentence as PLCG2 in open-access papers (continued):
Sharing a sentence is not in itself a finding about the gene and the disease.
synucleinopathies (1 paper, 2018). "It is therefore possible the ABI3 and PLCG2 variants may also influence risk of other neurodegenerative diseases including primary tauopathies and synucleinopathies." (PMID 30326945, 2018).
systemic lupus erythematosus (1 paper, 2020). An autoimmune multi-organ disease typically associated with vasculopathy and autoantibody production. "The top pathways predicted to be deactivated were systemic lupus erythematosus in B cell signaling pathway (Z-score = −0.333), melanocyte development and pigmentation signaling (Z-score = −1), and phospholipase C signaling (Z-score = −0.447) mainly elicited by TNF family regulators, LAT, and PLCG2." (PMID 32636844, 2020).
tauopathy (1 paper, 2022). Neurodegenerative disorders involving deposition of abnormal tau protein isoforms (tau proteins) in neurons and glial cells in the brain. "However, we did not observe any increase in Plcg2 expression in a 12-month tauopathy mouse model (P301S), which exhibits robust microgliosis." (PMID 35180881, 2022). "Interestingly, we did not observe an increase in Plcg2 expression in a 12-month tauopathy mouse model (P301S), which exhibits robust microgliosis, suggesting that the increase of Plcg2 might result from an association between microglia and amyloid plaques, rather than microgliosis." (PMID 35180881, 2022).
tuberculosis (1 paper, 2021). A chronic, recurrent infection caused by the bacterium Mycobacterium tuberculosis. "PLCγ2 was also found to be phosphorylated (at Y1217) by Mycobacterium tuberculosis (the causative agent of tuberculosis (TB)) in the macrophage cell lines." (PMID 34157287, 2021).
viral myocarditis (1 paper, 2023). Myocarditis that is caused by an infection with a viral agent. "SARS-CoV-2 infection may lead to viral myocarditis, which may be associated with the expression of PLCG2." (PMID 37109540, 2023).
Wilms tumor (1 paper, 2021). An embryonal neoplasm characterized by the presence of epithelial, mesenchymal, and blastema components. "PLCγ2 was implicated in the Wnt signaling pathway necessary for kidney development and development of Wilms' tumor." (PMID 34157287, 2021).
tumor (44 papers, 2011 to 2026). "PLCG2 has been implicated in the regulation of cell proliferation, transformation, and tumor growth and reported as an important oncogene in various cancers." (PMID 37031207, 2023). "PLCG2 is determined as a potential indicator of TME remodeling in tumor, and dysfunction of PLCG2 is closely associated with inflammation, immune disorders, and cancer." (PMID 36246627, 2022). "Among the 7 signature-associated genes, PLCG2 has been involved in regulating cell proliferation, transformation, and tumor growth." (PMID 35309940, 2022). "PLCG2 was closely associated with tumor immunosuppressive microenvironment, but whether PLCG2 could influence the response of CRC patients to immunotherapy remained unclear." (PMID 39494327, 2024). "There was also a strong association between PLCG2 and tumor drug resistance." (PMID 39494327, 2024). "On the other hand, while PLCγ2 has been implicated in the proliferation and migration of several human cancers, its genetic deletion in mice resulted in increased tumor growth." (PMID 32637413, 2020). "Targeting PLCG2 can inhibit tumor progression, regulate the tumor immune microenvironment, and enhance immune checkpoint blockade therapy in CRC." (PMID 40308582, 2025). "adopted scRNA‐seq to investigate the heterogeneity and tumor microenvironment of SCLC and identified a PLCG2‐high‐expressing subpopulation associated with metastasis and poor prognosis." (PMID 39974662, 2025). "The growth curves of subcutaneous tumors also showed that overexpression of PLCG2 promoted tumor growth in vivo, and knockdown of PLCG2 inhibited tumor growth." (PMID 39494327, 2024). "To determine the potentiating effect of knockdown of PLCG2 on anti-PD-1 therapy, we compared the tumor inhibition rate of this therapy in the control group (shnc-PLCG2) with that in the knockdown group (sh-PLCG2)." (PMID 39494327, 2024). "To explore the mRNA expression profile of PLCG2 in pan-cancer, we examined the mRNA expression differences of PLCG2 between tumor and normal tissues in TCGA public database." (PMID 39494327, 2024). "Single-cell transcriptional profiles of six CRC tissue specimens were revealed to investigate the important role of PLCG2 in the CRC tumor microenvironment." (PMID 39494327, 2024). "In vivo experiments showed that the tumor volume and weight of the synergistic therapy group (sh-PLCG2+anti-PD-1) were significantly lower than those of other groups." (PMID 39494327, 2024). "IHC experiments were carried out for further validation, of which the results indicated that tumor tissues exhibited significantly higher PLCG2 protein expression than the matched normal ones." (PMID 39494327, 2024). "In the TCGA-COAD and TCGA-READ cohorts, a higher PLCG2 mRNA expression was observed in tumor tissues." (PMID 39494327, 2024). "We delved into the role of PLCG2 on the metastatic capability of tumor cells by in vitro experiments in CRC cells." (PMID 39494327, 2024). "Single-cell sequencing analysis enabled us to identify PLCG2 expression patterns in different tumor cell subpopulations and their interactions with other genes with a high-resolution view of the cellular heterogeneity in the tumor microenvironment." (PMID 39494327, 2024). "The results showed that the level of p-AKT CyclinD1 protein was significantly reduced after PLCG2 overexpression in the subcutaneous tumor tissues of the nude mice." (PMID 39108206, 2024). "PLCG2 mRNA expression in tumor tissues was significantly different from normal tissues in pan-cancer." (PMID 39494327, 2024). "There were significantly fewer PD-L1+Ep-CAM+ tumor cells in the knockdown of PLCG2 group (sh-PLCG2) than in the control group (shnc-PLCG2)." (PMID 39494327, 2024). "The results indicated that the synergistic therapy group (sh-PLCG2+anti-PD-1) exhibited higher tumor inhibition rate." (PMID 39494327, 2024). "The single-cell and spatial transcriptome revealed the role of PLCG2 in shaping the heterogeneity of the CRC tumor microenvironment." (PMID 39494327, 2024).
tumor (continued). "Given the important function of PLCG2 in remodeling CRC tumor microenvironment, we explored the relationship between PLCG2 and immunotherapy response in CRC." (PMID 39494327, 2024). "Plate colony formation assays were conducted on cells overexpressing PLCG2, revealing a reduction in tumor cell proliferation upon overexpression of the PLCG2 protein." (PMID 39108206, 2024). "Overall, this result suggested that PLCG2 promoted tumor cell proliferation, invasion, metastasis, and EMT and inhibited apoptosis through activation of the Akt-mTOR signaling pathway, thereby facilitating CRC progression." (PMID 39494327, 2024). "PLCG2 has been shown to be involved in tumor microenvironment (TME) remodeling and has been identified as an immune-related gene in soft tissue sarcomas and colon cancer." (PMID 37031207, 2023). "Some CSC marker genes showed extremely disparate expression levels between normal and tumor samples, such as PLCG2, DDX11, IER5L, LENG8, HAGHL and CPNE7." (PMID 37377935, 2023). "Tumor tissues showed obviously higher expression levels of PLCG2, PLA2G4A, and HTR2C than the normal esophageal tissues." (PMID 35309940, 2022). "According to the database analysis, PLCG2 had low expression in tumour tissues, and the results of the experiments confirmed this conclusion." (PMID 35003085, 2021). "Recent evidence indicated that downregulation of PLCγ2 signaling results in the accumulation of immunosuppressive MDSCs in tumor-bearing mice instead." (PMID 32637413, 2020). "Thus, early genetic ibrutinib resistance mutations of PLCG2 may affect the biological impact of subsequent mutations, extending the concept of “genetic canalization” from tumorigenesis to development of resistance to targeted tumor drugs." (PMID 30344948, 2018). "Meanwhile, high expression of PLCG2 might promote the expression of PD-L1 and PD-1, thus hampering the killing effect of T lymphocytes on tumor cells, diminishing the efficacy of immunotherapy, and facilitating immune escape." (PMID 39494327, 2024). "Knockdown of PLCG2 significantly inhibited the tumor cell surface expression of PD-L1." (PMID 39494327, 2024). "Similarly, based on the integrated cohorts of TCGA and GTEx in the GEPIA2 database, we found significantly increased mRNA expression of PLCG2 in tumor tissues in READ, COAD, BRCA, and GBM." (PMID 39494327, 2024). "Spatial transcriptome sequencing analysis further complemented the single-cell sequencing technology by offering valuable insights into the spatial distribution of cells in tumor tissues, contributing to understanding the spatial heterogeneity of PLCG2 in the tumor microenvironment." (PMID 39494327, 2024). "The mIHC results of subcutaneous tumor tissues indicated a significantly lower expression of phosphorylated Akt proteins (Ser473 and Thr308) and phosphorylated mTOR proteins (Ser2481 and Ser2448) in oe-PLCG2+MK2206 group in contrast to oe-PLCG2 group." (PMID 39494327, 2024). "However, the part played by PLCG2 in the CRC tumor microenvironment and the regulatory mechanisms involved remained elusive." (PMID 39494327, 2024). "In summary, PLCG2 might be an important biomarker and therapeutic target for orchestrating the immunosuppressive microenvironment and suppressing tumor immune escape." (PMID 39494327, 2024). "In order to deeply resolve the biological roles and molecular mechanisms of PLCG2 in CRC, the present study employed a variety of bioinformatics analyses aimed at comprehensively revealing the biological function and mechanism of action of PLCG2 in tumor progression and tumor microenvironment." (PMID 39494327, 2024). "ICAM1, PLCG1, PLCG2 and other genes in the pathway are also related to tumor migration." (PMID 37312215, 2023). "In conclusion, PLCG2 may affect IL-6/JAK/STAT3 signaling pathway to form anti-tumor TME, which may depend on the subtype of STS and the role of STAT3 in TME." (PMID 33725976, 2021).
tumor (continued). "Interestingly, it has been shown that PLCγ2–/– mice exhibit increased tumor mass in the bone, despite the decreased osteoclast numbers." (PMID 32637413, 2020). "Looking downstream of PLCG2 in the KEGG pathway database, we hypothesize that a tumor with high recruitment of PLCG2 could be successfully treated with combinations of COX-, ERK-, and PKC-inhibitors." (PMID 30653502, 2019). "Moreover, previous studies have identified Btk, Blnk and PLCγ2 as potential tumor suppressors against pre-B cell transformation." (PMID 21818355, 2011). "PLCG2 was also found to be an essential regulator of CRC tumor microenvironment as it could inhibit immune-activated cell infiltration (CD8+ T cells) and promote immune-suppressed cell infiltration (Treg cells) and the expression of immune checkpoints, leading to the immune escape of CRC." (PMID 39494327, 2024). "For example, tumours from patients in cluster 1 (n = 11) had significantly more mutations (8.6 vs 3.5 in all other groups) and a significant enrichment of mutations and amplifications in genes from the ERBB signalling pathway (PLCG2, MAP2K7, ERBB4, and CAMK2B)." (PMID 33862582, 2021). "On the basis of these results, it appears likely that resistance to ibrutinib of tumor cells harboring a PLCG2 mutation is not an all-or-nothing, quantal process, but rather a graded response depending on both the site and the nature of the amino acid substitution within the PLCγ2 protein." (PMID 30344948, 2018). "The objective of our research was to explore the role of PLCG2 in CRC progression, tumor microenvironment, and potentiating ICB therapy." (PMID 39494327, 2024). "The integrated application of these bioinformatic methods not only deepened the understanding of the role of PLCG2 in CRC and the tumor microenvironment but also provided new strategies and molecular targets for CRC." (PMID 39494327, 2024). "We further validated PLCG2 mRNA expression in CRC by collecting 10 pairs of normal and tumor tissues from our center." (PMID 39494327, 2024). "It was noteworthy that the role of PLCG2 in CRC has rarely been investigated, and its relationship with the tumor microenvironment (TME) remained poorly understood." (PMID 39494327, 2024). "As the high expression of immune checkpoints (ICs) on the surface of tumor cells and immune cells contributed significantly to tumor immune escape, we investigated the expression of ICs in CRC patients with different PLCG2 expressions." (PMID 39494327, 2024). "The organoids derived from pathological tissues of CRC patients also confirmed that PLCG2 protein expression in CRC tissues and tumor organoids was significantly higher compared to matched normal tissues and normal intestinal epithelial organoids." (PMID 39494327, 2024). "Multiple mechanisms responsible for the resistance of BTK inhibitors include mutations in BTK and downstream signaling molecules, such as PLCγ2, CARD11, and BCL10 leading to prolonged and BTK-independent NF-κB activation resulting in tumor cell growth." (PMID 37845755, 2023). "SY-1530 inhibits the phosphorylation of BTK and the activity of BTK downstream kinases such as PLCγ2 and ERK, thus blocking the BCR signaling pathway and suppressing tumor growth in B-cell malignancies." (PMID 34264564, 2021). "The interaction between tumor cell PDPN and platelet CLEC-2 drives tyrosine phosphorylation of the Src family kinases (Syk) and phospholipase C gamma 2 (PLCγ2), resulting in platelet activation and aggregation." (PMID 31208371, 2019). "Similar to PLCγ2, the degree of both p-AKT and p-ERK inhibition is inversely correlated with the IC50 of cerdulatinib in 43 CLL samples suggesting the anti-tumor effect of cerdulatinib relates to its inhibition of distal signal transducers AKT and ERK." (PMID 28088788, 2017). "Acalabrutinib treatment significantly decreased the phosphorylation of PLCγ2 and ERK (P = 0.02), reduced tumor cell proliferation (P = 0.02), and tumor burden (P = 0.04)." (PMID 26957112, 2016).
tumor (continued). "This is the first study to identify that PLCG2 could be considered a precise biomarker and promising target for predicting CRC prognosis, individualized treatment, reversing tumor immune escape and overcoming the resistance to ICB therapy." (PMID 39494327, 2024). "They argued that high expression of PLCG2 might help form anti-tumor TME via IL-6/JAK/STAT3 signaling pathway, and then promote the proliferation, invasion and metastasis of tumor cells." (PMID 37074454, 2023). "To verify the results of our data analysis, we extracted total RNA from different tumour cell lines (HCT116, SW480, HT29, LOVO, RKO, DLD-1) and the normal epithelial colon cell line NCM460 and measured the mRNA expression levels of TIMP1, PLCG2, BDNF and IL13." (PMID 35003085, 2021). "Results revealed that PLCG2 may be a potential indicator of TME remodeling and may be involved in curbing STS tumor growth." (PMID 33725976, 2021). "NK cells also use PLCγ2 during their development and to elicit various cellular functions including CD69 signaling, secretion of cytotoxic granules, response to infection, and tumor immunosurveillance." (PMID 34157287, 2021). "Additional evidence for a potential role of the BCR pathway in the pathogenesis of MCL was provided by phospho-proteomic analysis of MCL cell lines and primary tumor samples demonstrating constitutive activation of multiple BCR signaling molecules, including CD79B, LYN, SYK, BLNK, BTK, and PLCγ2." (PMID 32481736, 2020). "Additional support for an involvement of the BCR pathway in the pathogenesis of WM came from observations that a number of BCR signaling molecules, including SFK, SYK, BTK, BLNK, PLCγ2, ERK, AKT, and NF-κΒ, are constitutively activated in primary WM tumor cells." (PMID 32481736, 2020). "Identification of the relevant molecular mechanism is likely to facilitate the development of inhibitors specifically targeting S707 mutant, but not wild-type PLCγ2, in patients suffering from acquired tumor drug resistance or hereditary autoinflammation." (PMID 30344948, 2018). "Furthermore, PLCG2 could promote the expression of PD-L1 and PD-1, and suppress the functional activation of CD8+ T cells to enhance the tumor immune escape." (PMID 39494327, 2024). "The CCK-8 assay showed that the proliferation of the PLCG2 siRNA group was markedly inhibited, and the level of proliferating cell nuclear antigen (PCNA) was reduced in the PLCG2 siRNA group, which is a tumor cell proliferation factor related to the proliferation ability of cells." (PMID 37031207, 2023). "However, PLCγ2 does not behave like classical tumor suppressor as c-Myc induced leukemogenesis remains unaltered in the PLCγ2+/−Myc mice." (PMID 21818355, 2011). "Although PLCγ2 is not needed for T cell receptor signaling, altered CD8+ T cell activation was observed in PLCγ2–/– tumor-bearing mice." (PMID 32637413, 2020). "The signaling pathways that are activated downstream of the BCR in MZL cells have not been investigated in detail, but analysis of primary tumor samples by phospho-flow cytometry demonstrated constitutive activation of SRC family kinases, SYK, PLCγ2, and p65 NF-κB." (PMID 32481736, 2020).